MET (MET proto-oncogene, receptor tyrosine kinase)
Diseases named in the same sentence as MET in open-access papers (continued):
Sharing a sentence is not in itself a finding about the gene and the disease.
lung cancer (continued). "Aberrant MET mutations resulted in c-MET overexpression in endometrial cancer tissues, similar to that seen in lung cancer, indicating that c-MET overexpression alone can induce oncogenic transformation in vitro and in vivo." (PMID 34439385, 2021). "Crizotinib has shown promise as a targeted therapy in lung cancers with MET amplification, yet the development of acquired resistance remains a major problem." (PMID 35693217, 2021). "c-MET (hepatocyte growth factor receptor) aberrations have been well reported in many forms of cancers including lung cancer and metastatic malignancies." (PMID 34138386, 2021). "This project, therefore, aimed to evaluate the interaction between SIPA1 and HGF/MET, as well as their influence on lung cancer in terms of molecular activation, cellular behaviour and clinical relevance." (PMID 33917539, 2021). "Genetic alterations and concurrent alterations of c-MET/EGFR with other genetic alterations have been well reported in lung cancer, but were underreported in other solid cancers especially CRC, and hence our study is significant in this regard." (PMID 34512327, 2021). "For our work, we used a panel of nine human and mouse lung cancer cell lines (sensitive or CTD-resistant) with diverse mutational/oncogenic driver profiles (i.e., KRAS G12 mutants, MET amplification, EGFR exon 19 deletion, among others)." (PMID 33850249, 2021). "In our experience, we demonstrated that our narrow SiRe NGS fusion panel is a reliable tool to detect clinically relevant gene fusions and MET exon 14 skipping alterations in routine samples of lung cancer." (PMID 33406752, 2021). "MET inhibitor-sensitive lung cancers with high-level MET amp have been reported in the absence of other sensitizing MET alts, such as exon 14 skipping, particularly among those with higher MET to chromosome 7 ratios." (PMID 34677235, 2021). "The same co-amplification of MET and HGF is reported to be a relatively frequent genetic aberration of various cancer types including lung cancer or renal cancer serving as a useful target for anti-MET therapies." (PMID 34885093, 2021). "EBC-1 lung cancer cells have MET gene amplification and are dependent on c-Met oncogene for proliferation and survival." (PMID 33574356, 2021). "MET gene fusions have been primarily identified in lung cancer such as the HLA-DRB1-MET, KIF5B-MET, MET-UBE2H, and MET-ATXN7L1." (PMID 34867402, 2021). "Some studies have shown that the activation of MET signaling drove the resistance to EGFR inhibitors in lung cancer." (PMID 34761497, 2021). "In SK-MES1 lung cancer cells, qPCR showed the transcript level of MET was actually higher in SIPA1-KD cells compared to pEF-CT cells." (PMID 33917539, 2021). "For example, MET activation, by either gene amplification or ligand stimulation, accounts for 5–10% of lung cancer resistance to EGFR TKIs." (PMID 34071428, 2021). "Lung cancer is the leading cause of cancer-related deaths in the world, and mutations and deregulation of many proteins and pathways, including EGFR, ALK, ROS1, and MET, play a significant role in lung cancer occurrence and development." (PMID 34603447, 2021). "The expression of this axis was also viewed as a prognostic biomarker, representing the clinical response of patients with advanced lung cancer and prostate cancer to c-MET- and vascular endothelial growth factor receptor 2 (VEGFR2)-targeted therapy." (PMID 34722241, 2021). "MET amplification in EGFR-mutant lung cancer was first described in an in vitro selected drug-resistant cell line and subsequently established as a clinical marker of EGFR TKI resistance in patients." (PMID 34516823, 2021). "EGFR is a well-studied oncogene in lung cancers and gliomas, MET is also a frequent driver in lung cancers, and BRAF is a signature driver gene in melanoma." (PMID 34054918, 2021). "Among these proteins, we found that the p-MET was the most significantly decreased protein after LINC00857 knockdown in PC-9 lung cancer cells." (PMID 33312753, 2020).
lung cancer (continued). "Previous studies have suggested that depletion of TIGAR results in a decrease in MET expression in lung cancer cell lines, but we were unable to detect any difference in MET expression in our PDAC cells." (PMID 31983610, 2020). "Since its discovery in lung cancer and other solid tumor malignancies, research has been investigating potential targeting of MET through small molecule inhibitors or monoclonal antibodies." (PMID 32560187, 2020). "HSPB suppression can result in the apoptotic death of MET-addicted EBC-1 in lung cancer cells, and oncogene-addicted cells require HSPB for survival." (PMID 32848724, 2020). "We have previously found that cell proliferation was decreased in lung cancer cells after MET knockdown with siRNA." (PMID 33312753, 2020). "Taken together, these results indicate that ABN401 significantly suppresses tumor growth in a dose-dependent manner in a mouse xenograft model of MET-addicted gastric and lung cancer cells." (PMID 32549194, 2020). "Silencing of MIR22HG can also triggers cell survival/death signaling via oncogenes YBX1, MET, and p21 in lung cancer." (PMID 32127004, 2020). "Lipid rafts have been implicated in a variety of cellular processes, including signaling transduction of RTK 46, AXL 33 and c-MET 47 RTKs, by contributing to the pathophysiology of lung cancer and the acquired resistance to EGFR TKI." (PMID 33042262, 2020). "Heterodimers and cross-phosphorylation preferentially occurred in lung cancer cells with amplified MET ratios." (PMID 32316583, 2020). "Their results showed that lung cancer cell growth was inhibited by simultaneous treatment with gefitinib and MET inhibitor." (PMID 32070026, 2020). "c-MET inhibitors, have the potential to benefit subsets of lung cancer patients with specific genetic alterations." (PMID 31935818, 2020). "Preclinical and clinical evidence suggests a role for MET activation as both a primary oncogenic driver in subsets of lung cancer and as a secondary driver of acquired resistance to targeted therapy in other genomic subsets." (PMID 32549766, 2020). "The driver mutations in lung cancer are gene mutations in EGFR and KRAS proto-oncogene (KRAS), ALK rearrangements, and altered MET proto-oncogene (MET) signaling." (PMID 32219066, 2020). "Amplification of MET in lung cancer is a well-known mechanism of resistance to epidermal growth factor receptor-targeted tyrosine kinase inhibitors (EGFR-TKIs)." (PMID 32290402, 2020). "A dual blockade of EGFR and MET can significantly inhibit the proliferation several carcinoma cells, including lung cancer cells, head and neck cancer cells, and colon cancer cells." (PMID 32070026, 2020). "MET mutations have recently been shown to occur in 3 to 4% of NSCLC adenocarcinomas, 2% of squamous cell carcinomas, and 1 to 8% of other subtypes of lung cancers." (PMID 32850378, 2020). "Through gene sequencing, it can be seen that lung cancer-related genes such as epidermal growth factor receptor gene mutation, c-MET, ROS1, KRAS, and BRAF, play an extremely important role in diagnosis and treatment of lung cancer." (PMID 32316985, 2020). "Taken together with our data, these observations suggest that IQGAP1 Tyr-1510 phosphorylation is likely to occur in some lung carcinomas in which MET is up-regulated." (PMID 33087447, 2020). "MET alterations leading to exon 14 skipping occur in ~4% of lung carcinomas, resulting in MET activation and sensitivity to MET inhibitors." (PMID 32397295, 2020). "Similar effect was observed by Sun et al52 who showed that MiR‐329 caused down‐regulation of MET expression what led to decreased mRNA level of MMP‐7 and MMP‐9 and thus reduced cellular migration and invasiveness of lung cancer cells." (PMID 31638339, 2019). "MET amplification was observed in gefitinib-resistant lung cancer cases, suggesting a relationship between MET and drug resistance." (PMID 31366141, 2019).
lung cancer (continued). "Treatment of lung cancer cells with a combination of MET siRNA and EGFR siRNA enhanced the growth inhibiting effect of EGFR siRNA alone." (PMID 31557260, 2019). "Our results also showed that MET overexpression was related to immunosuppressive features in the tumor microenvironment of PD-L1high lung cancer." (PMID 31480591, 2019). "Using the EGFR lung cancer model as an example, hyperactivation of the MET pathway either by amplification or by increased receptor protein expression and phosphorylation accounts for 5–10% of all patients resistant to EGFR-TKIs." (PMID 31815659, 2019). "The overexpression of miR-27a and the reduction of MET protein expression revealed that genistein has anti-cancer effects on lung cancer cells in a dose-dependent manner." (PMID 31480720, 2019). "MET Y1003X mutations, which abolish the binding domain of the E3 ubiquitin-protein ligase, c-CBL, disrupt degradation, and prolong the activation of MET signaling, are extremely rare and are far below 0.1% in lung cancers." (PMID 31369639, 2019). "Clinical trials for MET-targeted therapies are ongoing for patients with lung cancer and colorectal cancer based on the pro-tumorigenic role of MET (NCT 01982955, NCT 02132598 and NCT 02510001)." (PMID 31480591, 2019). "MET knockdown in two MET-amplified lung cancer cell lines (EBC-1, H1993) resulted in growth inhibition." (PMID 31557260, 2019). "Currently, the therapeutic options for patients affected by MET-altered lung cancer in an advanced stage are limited to clinical trials, using crizotinib or other more recently developed MET inhibitors." (PMID 30459450, 2019). "TheMiR-27a expression levels were activated through a decrease of the MET protein expression levels in lung cancer cells after genistein treatment." (PMID 31480720, 2019). "MET activation can also serve as a primary oncogenic driver or a secondary driver of acquired resistance to targeted therapy in different subsets of lung cancer." (PMID 31867280, 2019). "Upregulation of the receptor tyrosine kinase MET has been described in DMS114 lung cancer cells (FGFR1 amplified), made resistant to infigratinib and H1581 lung cancer cells (FGFR1 amplified) made resistant to AZD4547 and the FGFR inhibitor rogaratinib." (PMID 35582593, 2019). "The resulting network includes 43 TKs and 415 inferred, LUAD-specific substrates, which were validated at >60% accuracy by SILAC assays, including “novel’ substrates of the EGFR and c-MET TKs, which play a critical oncogenic role in lung cancer." (PMID 30615629, 2019). "Experiments in lung cancer cell lines (H358, H1650, H1975) revealed an effect of MET inhibition with su11274 and afatinib treatment on cell growth and apoptosis." (PMID 31557260, 2019). "Recently, reactivation of MAPK pathway, mediated by NRAS amplification or MET transcriptional regulation, has been linked to the emergence of resistance to FGFR inhibitors in FGFR1-amplified lung cancer cell models." (PMID 30972293, 2019). "In H358, H1650 and H1975 lung cancer cell lines, the inhibition of MET showed only weak effects on cell growth and apoptosis." (PMID 31557260, 2019). "IGFBP3 up-regulation in lung cancer cells leads to increased MET expression via Smad2/3 activation and results in EGFR- and Met-TKI dual resistance." (PMID 30609749, 2019). "KIT amp, EGFR amp, MET amp and ALK mutation in lung cancer, and CCNE1 amp in breast cancer were curated as resistant information only in the QCII." (PMID 31383922, 2019). "Other observations that were of potential clinical relevance were that the brain metastasis of lung carcinoma expressed relatively high levels of MET, RON and CTLA-4." (PMID 31747973, 2019). "Conversely, it is well known that inhibition of MET activity in MET-amplified lung cancer cells triggers a profound reduction of phosphoAKT (pAKT), indicating that AKT is a downstream effector of MET." (PMID 30140389, 2018).
lung cancer (continued). "ABT-700 (h224G11): The anti-c-Met monoclonal antibody ABT-700 has anti-tumor effects in lung cancer xenografts with amplification of MET gene." (PMID 30134579, 2018). "The second mechanism of MET regulation by TGFβ1 is related to suppression of miR‐128‐3p which, in turn, directly targets MET, which is in line with Jiang and colleagues non‐small cell lung cancer, and thereby impairs HGF/MET‐mediated cell migration." (PMID 30004628, 2018). "MET amplification is a mechanism of resistance to epidermal growth factor receptor-targeted tyrosine kinase inhibitors (EGFR-TKIs) in lung cancer." (PMID 30469509, 2018). "In lung cancer, amplification of MET is reported to be a mechanism of resistance to epidermal growth factor receptor-targeted tyrosine kinase inhibitors (EGFR-TKIs)." (PMID 29890660, 2018). "Overexpression of c-MET was found in 25–75% lung cancer patients, gene amplification has been observed in 5–22%,and mutations in about 5% of tumors." (PMID 29416799, 2018). "In fact, in lung cancer cells with c-Met amplification, HGF has been shown to be responsible for the observed resistance to anti-MET treatment." (PMID 30214428, 2018). "At present, ongoing phase I/II clinical trials are being carried out with c-MET inhibitors on patients with lung cancer, and some of them have shown the effect of inhibiting tumor growth." (PMID 29416799, 2018). "c-MET expression can be observed in the cytoplasm of lung cancer cells, and was detected in 56 cases." (PMID 29416799, 2018). "On the other hand, overexpression of HGF was identified in 61% of lung cancer patients with resistance to EGFR-TKIs overlapping MET amplification." (PMID 29890660, 2018). "MET is considered a strong candidate given its response to crizotinib, currently a treatment for ALK- and ROS1-rearranged lung cancers, however, MET alterations are uncommon, occurring in approximately 5% of NSCLC." (PMID 29914100, 2018). "Lung cancer cell lines treated with EGFR TKI gefitinib developed acquired resistance due to MET overexpression." (PMID 29325228, 2018). "HGF‐dependent MET activation via endocrine, paracrine or autocrine signaling had been observed in lung cancer." (PMID 29570930, 2018). "Previous studies describe much variation in the frequencies of MET protein overexpression (25–75%) and copy number variation (3.8–21%) in lung cancer, largely due to the use of different methods and specimens obtained in primary site or metastatic tumors." (PMID 29416799, 2018). "In nonsmall cell lung cancer (NSCLC), the EGFR V843I mutation and MET amplification were described as resistance‐supporting in afatinib therapy." (PMID 29325228, 2018). "In contrast to this, overexpression of HGF is seen in a significant number of lung cancer patients with EGFR-TKIs-resistance overlapping MET amplification." (PMID 30469509, 2018). "Here we established that SRI31215, and peptide-based inhibitors of pro-HGF activation, block the tumor-promoting activity of fibroblasts and overcome the resistance of MET-amplified lung cancer cells to anti-MET therapy." (PMID 28968967, 2017). "We previously reported that lung cancer cell lines had increased expression of c-MET due to gene amplification-induced cytotoxic drug resistance, and that resistant cells paracrine HGF and promote its resistance." (PMID 29069748, 2017). "In this study we have demonstrated that the responses to MET inhibition in an in vitro and in vivo lung cancer model differed depending on the EGFR genotype." (PMID 28141869, 2017). "Surprisingly, it has recently been shown that MET-amplified lung cancer cells become dependent on HGF for survival upon pharmacologic MET inhibition." (PMID 28968967, 2017). "After multiple-testing correction, 112 SNPs in eight genes (ATR, EGFR, MET, PIK3R1, PIK3R3, PTPN2, STAT3, and STAT5A) remained significantly associated with lung cancer risk with FDR <0.20." (PMID 28400551, 2017).
lung cancer (continued). "To understand how HGF signals in MET-amplified lung cancer cells when MET kinase activity is inhibited, we used the Proteome Profiler Human Phospho-RTK array (R&D Systems) to investigate the phosphorylation profiles of 49 different receptor tyrosine kinases." (PMID 28968967, 2017). "Here we aim at investigating PD-L1 expression in erlotinib-resistant lung cancer cells with MET proto-oncogene (MET) gene amplification." (PMID 28978110, 2017). "Lung cancer cells that were initially sensitive to the EGFR kinase inhibitor gefitinib developed resistance via the amplification of c-MET." (PMID 29291022, 2017). "We demonstrated that novel inhibitors of HGF activation overcome fibroblast-mediated resistance to MET inhibition in MET-amplified lung cancer cells." (PMID 28968967, 2017). "HGF-producing fibroblasts promote the survival and migration of MET-amplified lung cancer cells when MET is inhibited." (PMID 28968967, 2017). "In lung cancer, ectopic expression of miR-1 reduced the protein levels of MET, Pim-1, FoxP1, and HDAC4 to influence the survival of cancer cells and oncogenic properties." (PMID 28537886, 2017). "MET-amplified lung cancers, which display ligand-independent MET activation, are addicted to MET signaling and are extremely sensitive to MET inhibition." (PMID 28968967, 2017). "Here we demonstrated that HGF also drives resistance to anti-MET therapy in MET-amplified lung cancer cells." (PMID 28968967, 2017). "Collectively, our data show that fibroblasts elicit resistance to MET-targeted therapy through HGF in MET-amplified lung cancer cells." (PMID 28968967, 2017). "This demonstrates that MET-amplified lung cancer cells display selective sensitivity to MET kinase inhibition." (PMID 28968967, 2017). "In line with this, c-MET amplification was observed in 22% of lung cancer samples that had developed anti-EGFR therapy." (PMID 29291022, 2017). "Greater success has been seen in studies of the EGFR mutant lung cancer population in the setting of acquired EGFR kinase resistance, and those that select for MET activation (e.g. amplification, high copy number, mutations)." (PMID 29050231, 2017). "Recently, splice alterations in exon 14 of the MET gene (METex14), that are found in about 3% of human lung cancers, have been found to be associated with in vitro and clinical sensitivity to the c-MET TKI capmatinib and the ALK/ROS1/MET TKI crizotinib." (PMID 28315949, 2017). "Overexpression of miR-206 was also used to treat lung adenocarcinoma cisplatin-resistant cells to enhance MET protein level and, in turn, restrict the migration and invasion of lung cancer cells." (PMID 28701377, 2017). "Volitinib is a highly selective small molecule, ATP-competitive MET kinase inhibitor being investigated as a monotherapy for MET-amplified cancers, such as gastric and lung cancer." (PMID 27013592, 2016). "In our present research, silence of MET expression inhibited lung cancer cell lines (A549 and H1299) growth, migration, invasion and promoted apoptosis." (PMID 26909600, 2016). "For example, it has been demonstrated that lung cancer cells with amplified MET become dependent on HGF under pharmacological MET inhibition." (PMID 27121052, 2016). "In one study involving lung cancer patient samples, they found a correlation between Notch-1 and c-MET coexpression and a poorer prognosis." (PMID 27528792, 2016). "Further, we also discovered miR-329 targeting 3′-UTR of MET mRNA, and inhibiting the expression of MET in lung cancer cells (A549 and H1299), which further contributing to the growth-delay efficacy of miR-329." (PMID 26909600, 2016). "ALK rearrangement, MET amplification, BRAF mutation which account for 3–7%, 2–4%, and 1–3%, respectively, represent less frequent alterations in lung cancer." (PMID 27485414, 2016). "In patients with lung cancer, high level of consistency is seen between peripheral blood and tissue with regards to MET gene amplification." (PMID 27421137, 2016).